BRAF (B-Raf proto-oncogene, serine/threonine kinase)
Diseases named in the same sentence as BRAF in open-access papers (continued):
Sharing a sentence is not in itself a finding about the gene and the disease.
thymoma (7 papers, 2018 to 2025). A neoplasm arising from the epithelial cells of the thymus. "On the other hand, alterations in RTK–RAS family signaling cascade were detected only in recurrent thymomas (FGFR1/4, BRAF) (13%)." (PMID 39273507, 2024). "In the thymoma cell line Thy0517, it was found that the expression of GRB2 and the phosphorylation levels of BRAF, MEK1/2, and ERK1/2 in the MAPK pathway were positively correlated with the change in KITLG." (PMID 32463597, 2020). "To confirm this point, we used established AB thymoma cell line Thy0517 and the results showed that KITLG suppression could downregulate the expression of GRB2, p‐BRAF, p‐MEK1/2, and p‐ERK1/2, whereas KITLG overexpression had a profound activating effect on the MAPK pathway in Thy0517." (PMID 32463597, 2020).
vascular tumor (7 papers, 2018 to 2025). "Recently, pyogenic granuloma samples were reported to harbor BRAF and RAS mutations, suggesting that this may be a vascular tumor." (PMID 32293476, 2020).
alopecia (6 papers, 2012 to 2024). Hair loss usually from the scalp. "In our study, 10.3% of patients in the BRAF and MEK treatment group developed alopecia, compared with 37.59% in the BRAF inhibitor alone control group." (PMID 39776585, 2024). "Targeted therapies that can induce alopecia include multikinase inhibitors, BRAF inhibitors, FGF inhibitors, hedgehog inhibitors, and CD4 inhibitors." (PMID 37925388, 2023). "BRAF inhibitors lead to initial alopecia in ≈20% of patients, although hair regrowth may occur despite continued treatment." (PMID 34771716, 2021). "Notably, while the use of trametinib (MEK inhibitor) leads to alopecia in about 13% of cases, dual BRAF/MEK inhibition with vemurafenib/cobimetinib or dabrafenib/trametinib leads to alopecia in 13% and 6% of cases, respectively." (PMID 34771716, 2021). "Beside these advantages, we also observed that combination of BRAF and MEK inhibition carried lower risks of arthralgia, hand-foot syndrome and alopecia than BRAF inhibition monotherapy." (PMID 28416755, 2017).
anemia (6 papers, 2017 to 2025). A reduction in the number of red blood cells, the amount of hemoglobin, and/or the volume of packed red blood cells. "Together, these results provide evidence that BRAF inhibitors promote human hematopoietic and erythroid development in mouse models, while also highlighting the potential of BRAFi to alleviate anemia in vivo." (PMID 39617757, 2024). "We uncovered BRAF inhibitors as promising agents for boosting erythroid progenitor cell proliferation and differentiation, paving the way for novel treatments for a variety of anemia conditions, including DBA." (PMID 39617757, 2024). "In addition to extensive characterization of the associations between blood Hb and systemic inflammation, this is, to our knowledge, the first study to analyze the correlations between different anemia subgroups in CRC and MMR enzyme status and BRAF mutation." (PMID 29348549, 2018). "For instance, BRAF V600E-driven MAPK pathway activation leads to cytopenias, including monocytopenia, which are often accompanied by neutropenia, anemia, and thrombocytopenia." (PMID 40421333, 2025). "In summary, our study highlights the potential value of BRAF inhibitors in treating anemia, from their therapeutic effects observed in vitro to their efficacy in DBA animal models, offering promise for improving outcomes in patients with refractory anemia and related disorders." (PMID 39617757, 2024).
Anxiety (6 papers, 2012 to 2025). Intense feelings of nervousness, tension, or panic often arise in response to interpersonal stresses. "Although depression and anxiety were not assessed as independent variables, the multidimensional structure of the BRAF–MDQ, which includes cognitive and emotional components, indirectly captured certain aspects of psychological burden." (PMID 41509951, 2025). "Four weeks after the completion of induction Braficko/adult mice were analyzed for anxiety-related and depression-like behavior in the elevated plus maze (EPM) and the forced swim test (FST) respectively, followed by the confirmation of BRAF depletion in brain sections." (PMID 22529971, 2012).
bowel cancer (6 papers, 2023 to 2024). "This is consistent with our findings that there was an association between BRAF MSS bowel cancer and its late-stage diagnosis." (PMID 37620872, 2023). "One investigation indicated that the pairing of BRAF inhibitors with EGFR monoclonal antibodies encouraged a temporary MSI-H phenotype in MSS-type bowel cancer, hinting at potentially improved survival outcomes for patients harboring BRAF mutations." (PMID 37927605, 2023). "We use serial monitoring of circulating tumor DNA cell-free plasma DNA (cfDNA) in a patient case study in addition to organoids derived from mouse models of BRAF-V600E-mutant intestinal cancer, which emulated the patient's mutational profile to assess drug treatment efficacy." (PMID 39626159, 2024).
cardiac hypertrophy (6 papers, 2018 to 2024). "They reported that loss of BRAF attenuated both pathological cardiac hypertrophy and interstitial fibrosis." (PMID 36651286, 2023). "RAF kinases (ARAF/BRAF/RAF1) integrate signals into the extracellular signal-regulated kinase 1/2 cascade, a pathway implicated in cardiac hypertrophy, and activation of BRAF in cardiomyocytes promotes compensated hypertrophy." (PMID 36331065, 2022). "In contrast, encorafenib activates ERK1/2 signalling (via the RAF paradox) and promotes compensated cardiac hypertrophy in a similar manner to knock-in of the BRAF(V600E) mutation." (PMID 36331065, 2022). "In particular, RAF kinases (ARAF/BRAF/RAF1) have already been identified as key regulators during cardiac hypertrophy in mice." (PMID 38892401, 2024). "AKT activation and cardiac hypertrophy were also observed in transgenic mice expressing BRAF-V600E from the endogenous locus, while ERK activity remained unaffected." (PMID 38266090, 2024). "Recently, two studies originating from the same group have provided novel insights into the role of BRAF in cardiac hypertrophy." (PMID 36651286, 2023). "To gain further insight into the consequences of cardiomyocyte BRAF knockout for the heart in AngII-induced cardiac hypertrophy, we assessed mRNA expression of selected genes." (PMID 36331065, 2022). "Nevertheless, BRAF remains a significant therapeutic target for cancer and our data show that it is an important regulator of cardiac hypertrophy at least in male mice." (PMID 36331065, 2022). "Overall, the data indicate that activation of endogenous cardiomyocyte BRAF induces cardiac hypertrophy and enhances cardiac function." (PMID 35147166, 2022). "As in previous studies, phenylephrine promoted cardiac hypertrophy as assessed by echocardiography with decreased LV internal diameter and increased wall thickness, and neither appeared to be significantly affected in hearts of mice with cardiomyocyte BRAF knockout." (PMID 36331065, 2022). "Interstitial fibrosis with physiological cardiac hypertrophy was sporadic in female mice and not affected by BRAF knockout." (PMID 36651286, 2023).
COVID-19 (6 papers, 2020 to 2025). A disease caused by infection with severe acute respiratory syndrome coronavirus 2. "Reported associations include vaccinations (hepatitis B, COVID-19), pharmacological agents, such as interferon-alpha and ribavirin for hepatitis C, immune checkpoint inhibitors (nivolumab), and BRAF/MEK inhibitors (encorafenib and binimetinib)." (PMID 41523385, 2025). "The device’s clinical utility is demonstrated in cancer mutations-analysis during the detection of 0.01% of BRAF-V600E-to-wild-type molecules from tissue samples and COVID-19 testing with 97% (Ct < 36.8) and 98% (Ct < 30) sensitivity when using extracted RNA and nasopharyngeal-swabs, respectively." (PMID 35260588, 2022). "One case of each EGFR, ALK, ROS1, and BRAF genetic alteration were found in the COVID-19 patients." (PMID 33042826, 2020).
dermatitis (6 papers, 2013 to 2025). An inflammatory process affecting the skin. "Recently, mice with epidermis-specific BRAF/RAF1 deficient also showed AD-like dermatitis, which is characterized by increased serum IgE levels and a Th2 response." (PMID 32792500, 2020). "The anti-inflammatory properties of JNK-inhibitors have also been described for BRAF-inhibitor-induced skin inflammation in vivo." (PMID 34833113, 2021). "In 2012, the first patient suffered from radio-dermatitis after concomitant radiotherapy and treatment with the BRAF inhibitor Vemurafenib." (PMID 34073147, 2021).
malignant peripheral nerve sheath tumor (6 papers, 2020 to 2025). Malignant peripheral nerve sheath tumor (MPNST) is a rare and often aggressive soft tissue sarcoma occurring in a wide range of anatomical sites. "However, there are several case reports of the presence of the BRAF mutation in different sarcoma subtypes, like malignant peripheral nerve sheath tumors (MPNST), GIST and Ewing sarcoma." (PMID 33799327, 2021).
neuroepithelial tumor (6 papers, 2017 to 2026). "Histopathological and genomic analyses confirmed the tumor as BRAF V600E-mutated polymorphous low-grade neuroepithelial tumor of the young (PLNTY)." (PMID 32811569, 2020). "BRAF gene mutation has been found in 43.8% solitary DIA/DIGs recently, which hinted DIA/DIGs were another low-grade MAPK pathway-driven neuroepithelial tumor and might allow for the use of targeted molecular therapies, such as vemurafenib." (PMID 35615429, 2021). "Recent molecular genetic studies have revealed various mutations in the mitogen-activated protein kinase (MAPK) pathway, including BRAF and FGFR1, in low-grade neuroepithelial tumors; however, associations between genotypes and pathological findings remain unclear." (PMID 39081340, 2024).
ocular melanoma (6 papers, 2010 to 2024). A melanoma that arises from the structures of the eye or ocular adnexa. "However, the same group later used IHC and found increased expression of BRAF protein in feline ocular melanomas." (PMID 38787171, 2024). "Thus, further research is needed into the role of BRAF in feline ocular melanomas." (PMID 38787171, 2024). "Further studies are needed to assess the efficacy of BRAF and PD1 inhibitors in the different subtypes of ocular melanoma." (PMID 27520988, 2016). "For many years it was thought that patients with ocular melanoma could not benefit from treatment with BRAF-kinase inhibitors due to the fact that the RAS-BRAF kinase pathway is not involved in the most common ocular melanoma, the choroidal melanoma." (PMID 27520988, 2016). "However, BRAF therapy is not established for patients with CMM or other ocular melanomas." (PMID 27520988, 2016).
panuveitis (6 papers, 2015 to 2024). A disorder characterized by inflammation of the entire uvea which includes the iris, ciliary body, and choroid. "Our data demonstrated a statistically significant association between BRAF inhibitors, especially dabrafenib, with panuveitis, anterior uveitis, and overall ciliary body and iris anomalies." (PMID 37347077, 2023). "In this article, we report a case of severe bilateral panuveitis during melanoma therapy with a combination of Dabrafenib, a B-raf (BRAF) inhibitor, and Trametinib, a mitogen/extracellular signal-regulated kinase (MEK) inhibitor." (PMID 26078801, 2015). "We report a case of severe bilateral panuveitis during melanoma therapy with a combination of Dabrafenib, a B-raf (BRAF) inhibitor, and Trametinib, a mitogen/extracellular signal-regulated kinase (MEK) inhibitor." (PMID 26078801, 2015). "The mechanism behind BRAF/MEK inhibitor induced panuveitis, which clinically closely resembles the VKH disease, might be related to its interference with the MAPK pathway, which is involved in the T-cell receptor signaling pathway." (PMID 37589912, 2023).
pulmonary embolism (6 papers, 2019 to 2025). The obstruction of the pulmonary artery or one of its branches by an embolus, sometimes associated with infarction of the lung. "It improves the effectiveness of BRAF inhibitors, such as dabrafenib, but increases the risk of pulmonary embolism at least 4-fold compared to BRAF monotherapy, as seen in a systematic review and meta-analysis." (PMID 39519000, 2024). "The incidence of pulmonary embolism was 2.2% in the combination group compared with 0.4% in the BRAF inhibitor monotherapy group." (PMID 35492830, 2022). "Analysis revealed that therapy with BRAF and MEK inhibitors was associated with a risk of pulmonary embolism (RR, 4.36; 95% CI, 1.23-15.44; P = .02; I2 = 0%), with 2.2% of patients from the BRAF and MEK group developing pulmonary embolism compared with 0.4% of the BRAF inhibitor monotherapy group." (PMID 31397860, 2019).
renal tumors (6 papers, 2013 to 2025). "BRAF mutation has been reported in 90% cases in a series of MA studies but it is rarely detected in other kidney tumors, including WT." (PMID 23599785, 2013). "It was demonstrated that missense mutation of BRAF V600E could be detected in approximately 90% of this kidney tumor subtype." (PMID 30111351, 2018). "Moreover, BRAF V600E mutations in common non-MA renal tumors were either extremely infrequent (less than 1%) or absent." (PMID 36313688, 2022). "Thus, since BRAF V600E gene is extremely infrequent or absent in non-MA renal tumors, its high mutation rate led to its application as a specific marker for MA." (PMID 36313688, 2022). "Nevertheless, as BRAF V600E mutation is quite rare or even absent in other common renal tumors, it could be used as a molecular marker for the detection of MA." (PMID 30111351, 2018). "To validate and extend our findings, we screened IFS and a range of childhood renal tumors for EGFR-ITD, BRAF-ID, and ETV6-NTRK3 using PCR." (PMID 29915264, 2018).
signet ring cell carcinoma (6 papers, 2011 to 2022). A usually aggressive, poorly differentiated invasive adenocarcinoma characterized by the presence of malignant glandular cells in which the nucleus is pressed to one side by the presence of intracytoplasmic mucus. "BRAF mutation is associated with poor prognosis, and is more frequent in signet ring cell carcinoma than AC." (PMID 32582557, 2020). "Mutation rates of BRAF are reported to be higher in signet ring cell carcinoma than in AC." (PMID 32582557, 2020). "The presence of peritoneal metastasis, BRAF mutation, unfavorable histology (poorly differentiated adenocarcinoma or signet ring cell carcinoma), and PTL were statistically meaningful parameters in bivariate analysis for OS and PFS using the Cox proportional hazard model." (PMID 29169325, 2017). "Their studies showed that 22% and 33% BRAF mutation in signet-ring cell carcinomas, respectively." (PMID 27300552, 2016). "For example, the IDH1 mutations we detected by NGS in Idylla-detectable BRAF or KRAS mutation positive CRC specimens are associated with mucinous or signet ring cell adenocarcinoma, thus providing molecular support for the correct diagnosis that would not be possible from the Idylla results." (PMID 35627184, 2022). "However, 60.0% (9 out of 15) of CRC cases with BRAF mutation were of the por or muc subtypes, although no signet-ring cell carcinomas were observed." (PMID 21285991, 2011).
spindle cell neoplasm (6 papers, 2014 to 2025). A benign or malignant neoplasm characterized by the presence of neoplastic spindle cells. "Undifferentiated spindle cell neoplasms with NTRK-rearrangement (or activating mutations in RAF1, BRAF, RET, MET, and others) are rare, recently described lesions in children." (PMID 40491214, 2025). "The identification of a BRAF fusion in this spindle cell tumor is consistent with molecular and phenotypic correlation of an activated BRAF in some MPNST cases." (PMID 24422672, 2014). "Recently, a novel group of CD34 and S100 co-expression spindle cell tumors with distinctive stromal and perivascular hyalinization harboring recurrent gene fusions involving RET, RAF1, BRAF, and NTRK1/2 gene has been identified." (PMID 36229858, 2022). "When the immunoprofile is not consistent with that of common spindle cell tumors, immunostaining for FDC markers such as CD21, CD23, and CD35, as well as further immunohistochemistry for D2-40, CD68, EGFR, EBV, and BRAF can be helpful for the diagnosis and subtyping of FDCS." (PMID 34516525, 2021).
spindle cell sarcoma (6 papers, 2024 to 2025). A malignant mesenchymal neoplasm composed of spindle-shaped cells. "Case presentation: A 13-year-old girl was diagnosed with low-grade spindle cell sarcoma of pelvic localization, BRAF exon 15 double-mutated: c.1799T>A p.V600E and c.1819T>A p.S607T in cis-position." (PMID 39018206, 2024). "Here we describe a low-grade spindle cell sarcoma with double-mutated BRAF exon 15: c.1799T>A and c.1819T>A in cis-position, corresponding to V600E and S607T amino acid substitutions." (PMID 39018206, 2024). "This is the first report of spindle cell sarcoma BRAF V600E/S607T double-mutated, responding to a combination of B-Raf and MEK inhibitors." (PMID 39018206, 2024). "Here we describe a case of undifferentiated spindle cell sarcoma showing primary insensitivity to standard chemotherapy and pronounced but non-sustained response to BRAF/MEK inhibitors at recurrence." (PMID 39018206, 2024).
Thrombocytopenia (6 papers, 2015 to 2026). A reduction in the number of circulating thrombocytes. "Potential reasons include the inability to sustain BRAF inhibition in this combination, as 39% of patients required dose reduction and one death event occurred secondary to grade 4 thrombocytopenia." (PMID 36801912, 2023). "While these findings reveal that combining BRAF and BCL-XL inhibitors represents a promising therapeutic approach for BRAFV600E CRC, the clinical use of BCL-XL inhibitors is currently limited by their on-target toxicity of thrombocytopenia." (PMID 38429301, 2024).
venous thromboembolism (6 papers, 2017 to 2026). Occlusion of the lumen of a vein by a thrombus that has migrated from a distal site via the blood stream. "Excitingly, we found some unexpected and significant safety signals, which included BRAF V600E mutation positive, volvulus, hepatic function abnormal, and venous thromboembolism (VTE)." (PMID 36380085, 2022). "•BRAF inhibitor and MEK inhibitor combination therapy is associated with an increased risk of venous thromboembolism when compared with BRAF inhibitor monotherapy." (PMID 35492830, 2022). "Long-term administration of BRAF inhibitors has been observed to associate with a range of skin changes, febrile reactions, arthralgia, headache, venous thromboembolism, cardiomyopathy, and hyperglycemia." (PMID 29179523, 2017).